REN (renin)
Diseases named in the same sentence as REN in open-access papers (continued):
Sharing a sentence is not in itself a finding about the gene and the disease.
Hypertension (continued). "Hypertension is associated with the severity of kidney injury and the type of histological lesion, as well as with immune dysregulation and activation of the renin-angiotensin-aldosterone system, corticosteroid use, and accelerated atherosclerosis due to chronic inflammation." (PMID 39671453, 2025). "The common HF is typically induced by underlying cardiac disorders, such as hypertension, during which the activation of the sympathetic nervous system and the renin‐angiotensin‐aldosterone system is predominantly involved, which is less associated with glucocorticoids." (PMID 40642838, 2025). "In this case, the association between diabetes and hypertension might be due to the hemodynamic alteration that triggers renin-angiotensin-aldosterone system and changes in blood calcium level." (PMID 39883731, 2025). "Furthermore, this paper highlights the potential benefits of immunological approaches in managing the root causes of hypertension, offering an alternative to conventional therapies focused on the renin–angiotensin–aldosterone system." (PMID 41155215, 2025). "Several chemotherapeutic agents impair vascular endothelium, sympathetic nerve activity, and renin-angiotensin system activity, which makes hypertension the most common comorbidity associated with tumors, and some scholars have proposed the new concept of “onco-hypertension”." (PMID 40182041, 2025). "Through target functional clustering of absorbed prototypes of YLQGS, we identified a strong correlation between triterpenoids and Cluster 2 target genes, which is associated with the regulation of the Renin–Angiotensin–Aldosterone System (RAAS)—a well-established target for hypertension." (PMID 40445525, 2025). "Hypertension can be controlled by administering intravenous calcium channel blockers, while diuretics are avoided to prevent exacerbation of fluid and sodium loss and further stimulation of the renin–angiotensin–aldosterone system." (PMID 40493279, 2025). "Thus, increased aldosterone-to-renin ratio, together with hypertension and hypokalemia, is the hallmark of PA." (PMID 40309437, 2025). "In a global analysis, undiagnosed albuminuria was 20-times more prevalent than detected cases among adults with hypertension, and a positive uACR result was associated with a triple increase in the initiation of renin–angiotensin–aldosterone system (RAAS) blockade." (PMID 41345917, 2025). "Specifically, we hypothesized that TMAO exerts a protective effect against cardiovascular complications associated with hypertension by modulating the tissue renin-angiotensin system (RAS)." (PMID 40951831, 2025). "Furthermore, oxidative stress in rats with L-NAME-induced hypertension has been associated with the activation of the renin-angiotensin system (RAS)." (PMID 40872547, 2025). "In addition to these social factors, the patient underwent an extensive evaluation for secondary causes of hypertension, including renal artery Doppler imaging, thyroid function testing, plasma renin and aldosterone levels, and plasma/urine metanephrines." (PMID 40988971, 2025). "Additionally, activation of the renin-angiotensin-aldosterone system in individuals with hypertension has been implicated in processes such as cellular proliferation, inflammation, angiogenesis, and tissue remodeling, potentially increasing cancer risk." (PMID 40366326, 2025). "Hypertension may be caused by mechanisms including the activation of the renin-angiotensin system, oxidative stress, endothelial inflammation, endothelin-1 activation, and nitrous oxide reduction." (PMID 40000548, 2025). "By lowering renin levels, vitamin D may contribute to reducing blood pressure and mitigating the risk of hypertension." (PMID 39796548, 2024).
Hypertension (continued). "Results from multiple studies found that high eGCSS was associated with low renin levels and high albumin-creatinine ratio in hypertension, correlated with high salt intake in a similar population from Zambia, and was associated with hypertension despite use of antihypertensive medication." (PMID 38524849, 2024). "We acknowledge that the underlying disease processes in low-renin hypertension are varied.Conditions like Liddle-like syndrome and the use of epithelial sodium channel inhibitorsshould be considered in those who do not respond to mineralocorticoid receptor antagonisttherapy." (PMID 39281005, 2024). "Workup for secondary causes of hypertension revealed low renin levels with normal aldosterone." (PMID 39184766, 2024). "Finally, hypertension can cause abnormalities in the renin-angiotensin-aldosterone system, leading to dementia." (PMID 39328244, 2024). "Indeed, vitamin D has been implicated in the activation of the renin–angiotensin system, cardiac hypertrophy, and arterial hypertension in vitamin D receptor knockout mice." (PMID 39337248, 2024). "The underlying pathophysiological mechanisms of hypertension in hypothyroidism may involve changes in circulating catecholamines, catecholamine receptors, and the renin-angiotensin-aldosterone system." (PMID 38177993, 2024). "Our reported association of renin with higher CHD-risk might have been lost when using the fully-adjusted model due to the adjustment for hypertension." (PMID 38811951, 2024). "We hypothesize that in a large proportion of patients with low-renin hypertension, the underlying pathophysiology involves MR activation and therefore targeted treatment with an MRA will offer greater antihypertensive effects and end-organ protection." (PMID 39026100, 2024). "The endocrine component focuses on RAAS, which may contribute to hypertension development by some variants like high-profile renin hypertension, which occurs more often in the young male group." (PMID 39517332, 2024). "A vital role in the pathophysiology of hypertension is played by circulating miRNAs, which are becoming useful biomarkers in essential hypertension and are inherently associated with every element of the renin-angiotensin-aldosterone system." (PMID 38605867, 2024). "Obesity is a significant risk factor for hypertension and can lead to increased insulin resistance, activation of the renin-angiotensin-aldosterone system, and sympathetic nervous system dysregulation, all of which contribute to the development and exacerbation of hypertension." (PMID 38800155, 2024). "Inflammation near glomeruli and vascular fibrosis must be further investigated for their association with the renin–angiotensin pathway, as this could directly affect the cardiovascular system by increasing hypertension." (PMID 39273272, 2024). "This is also linked to reduced activity in the renin–angiotensin–aldosterone system, insulin resistance, augmented natriuretic peptide blood concentration, systemic inflammation, and arterial stiffness, all of which prevent the reappearance of hypertension." (PMID 39457606, 2024). "Furthermore, vitamin deficiency is associated with increased cardiovascular risk, especially among females, as it affects the renin–angiotensin–aldosterone system, potentially leading to vascular dysfunction and hypertension." (PMID 39477860, 2024). "Recent studies have consistently shown that chronic or recurrent dehydration is associated with chronic activation of the renin–angiotensin system, endothelin, vasopressin, and aldose-reductase–fructokinase pathway, which can subsequently lead to obesity, metabolic syndrome, hypertension, and CKD." (PMID 39518643, 2024). "Likewise, being overweight is a well established cause of high blood pressure involving several pathways, including stimulation of the renin–angiotensin–aldosterone system." (PMID 39457109, 2024).
Hypertension (continued). "The use of male rats in our experiment is significant because hypertension is linked with the renin–angiotensin–aldosterone system (RAAS), and it is evident that renal sympathetic nerve activity is less excitable and more easily repressed in females than males." (PMID 37571339, 2023). "Obesity and insulin resistance are both causal factors for hypertension, as insulin resistance and increased insulin levels have been linked to reduced release of nitric oxide, and activation of the renin-angiotensin pathway, causing blood vessel constriction and consequently high blood pressure." (PMID 37351191, 2023). "Angiotensin II (Ang II), a peptide hormone generated as part of the renin–angiotensin system, has been implicated in the pathophysiology of many cardiovascular diseases such as peripheral artery disease, heart failure, hypertension, coronary artery disease and other conditions." (PMID 36771035, 2023). "In this regard, a history of comorbidities have been reported as risk factors for severity of COVID-19, including hypertension due to the imbalance between the two major pathways of the renin–angiotensin–aldosterone system (RAAS), with ACE2/Ang 1-7 downregulation and ACE2/Ang II upregulation." (PMID 37762753, 2023). "In addition, an impaired renin-angiotensin system is an important risk determinant for hypertension, whereas low concentrations of VD are correlated with an impaired renin-angiotensin system (RAS)." (PMID 38161941, 2023). "Obesity may independently cause hypertension through several mechanisms including activation of the renin–angiotensin–aldosterone pathway." (PMID 37452142, 2023). "In obesity, hypertension is (at least partly) caused by salt-retention and associated with a low to normal renin production which in turn could trigger the kidney EGF production." (PMID 36996194, 2023). "The reason for this comorbidity remains unclear, but hypertension-induced inflammation or abnormal activation of the renin-angiotensin system are hypothesized to predispose individuals to insulin resistance, a strong risk factor for NAFLD." (PMID 37608217, 2023). "Nonetheless, the increased incidence of hypertension, fluid overload, and pathological activation of the intrarenal renin–angiotensin–aldosterone might explain this association." (PMID 36826578, 2023). "The main cancer-associated aspartic proteases are renin, cathepsins, pepsin C, and napsin A. In addition to hypertension, disturbances of the renin–angiotensin system are linked to pathways deregulated in the pre-cancerous stage and can influence immunosuppression in tumors." (PMID 38139365, 2023). "Vitamin D may also regulate the renin-angiotensin-aldosterone system, which is implicated in the development of hypertension and proteinuria in LN." (PMID 38111622, 2023). "Lead may exacerbate the damage to blood vessels through mechanisms such as enhancing oxidative stress and stimulating the renin–angiotensin–aldosterone system, with a consequent increased risk of hypertension, cardiovascular disease and kidney disease." (PMID 37574566, 2023). "Both Studies found that hypertension is the most common co-morbid condition, and this correlates with the pathophysiology of CKD-associated hypertension where renin-angiotensin-aldosterone system (RAAS) over expression accompanied by eGFR reduction results in sodium and water retention." (PMID 37250643, 2023). "Furthermore, inflammation, insulin resistance, and renin–angiotensin system–sympathetic nervous system activation were all critical pathophysiological mechanisms in the association between obesity and hypertension." (PMID 38089604, 2023). "The mechanism by which hyperuricemia causes hypertension involves the sympathetic nervous system hyperactivity, endothelial dysfunction with reduced NO levels, and renal vasoconstriction mediated by activation of the renin-angiotensin system." (PMID 37238926, 2023).
Hypertension (continued). "Some researchers have hypothesized that the cortical glomeruli entrapped by MST tumor cells induce hyperplasia of juxtaglomerular cells, subsequent secretion of renin, and cause hypertension." (PMID 37454137, 2023). "Hypothetically, the same signalling pathway may also be involved in the activation of juxta glomerular apparatus (JGA) cells causing the activation of the renin-angiotensin-aldosterone mechanism causing hypertension." (PMID 37583748, 2023). "Our results suggest that polymorphisms in the renin-angiotensin-aldosterone system could contribute to premature hypertension, endothelial dysfunction, atherothrombosis, vasoconstriction, smooth muscle cell migration, and proliferation." (PMID 38025202, 2023). "VC and osteoporosis may share common risk factors such as renin-angiotensin system (RAS)-related hypertension." (PMID 36838684, 2023). "In agreement, Carrara and colleagues showed in a population of 33 patients with hypertension and hypovitaminosis D that vitamin D supplementation at a dose a 50,000 IU/week for eight weeks was associated with a reduction in plasma renin activity (PRA), renin levels, and angiotensin II levels." (PMID 37371510, 2023). "The possible mechanism is that fat accumulation leads to high estrogen in the body, thus mediating aldosterone secretion, sodium retention caused by the renin-angiotensin system, or directly increasing the recollection of the renal tubules, resulting in hypertension." (PMID 37008898, 2023). "Likewise, elevated renin expression, an enzyme involved in the renin-angiotensin II-aldosterone axis regulating blood pressure, was associated with higher prevalence of hypertension in Cluster 1, as previously demonstrated." (PMID 36480517, 2022). "However increased SCFA can increase blood pressure by stimulating renin secretion, and Fusicatenibacter showed a significant association with systolic blood pressure and diastolic blood pressure in hypertension patients." (PMID 36301099, 2022). "This leads to an up-regulation of the renin-angiotensin system and is hypothesized as the reason behind the association of systemic hypertension with PASC." (PMID 35273894, 2022). "Almost all patients in our study cohort exhibited secondary arterial hypertension associated with renal dysfunction, as well as the triggering activation of the renin-angiotensin-system, resulting in high levels of renin among these selected patients with end-stage chronic kidney disease." (PMID 36077181, 2022). "However, in our candidate approach, we found that several DMPs previously associated with hypertension and kidney function were also associated with concentrations of renin, aldosterone, and ARR." (PMID 36457109, 2022). "Low-renin individuals could be at high risk of hypertension among Koreans, due to the genetic predisposition with high sodium uptake." (PMID 35448080, 2022). "Given that in these cases hypertension often persists even after surgery, sometimes associated with persistent increase of aldosterone to renin ratio, it would be more appropriate to first treat the patient with anti‐aldosterone therapy and then reconsider the possibility of surgery." (PMID 34847293, 2022). "Thus, the activated renin-angiotensin-aldosterone system (RAAS) is undoubtedly associated with the aggravation of hypertension in the male animals." (PMID 35242585, 2022). "The association of hypertension with MHO phenotype may arise from the activation of the renin-angiotensin-aldosterone and sympathetic nervous systems, oxidative stress, and altered cytokines." (PMID 36229850, 2022). "Activation of the renin–angiotensin system has been implicated in hypertension." (PMID 35721173, 2022). "Our results might be a valuable indicator for hypertension risk prediction and preventive measure, considering renin concentration with genetic susceptibility." (PMID 35448080, 2022).
Hypertension (continued). "Gestational diabetes stems from dysregulation of insulin and altered fatty acid metabolism while hypertension and preeclampsia may arise from underlying kidney disease or changes in the renin–angiotensin or sympathetic nervous systems." (PMID 36615797, 2022). "Thus, we investigated the genetic predisposition of the blood renin concentration, influencing future hypertension incidence, using a community-based Korean cohort, observed over 12 years." (PMID 35448080, 2022). "Intergenic CpGs cg18264657 and cg11710912 annotated to the ARGLU1 gene that were previously associated with hypertension in other study populations of European and South Asian ancestry were associated with renin concentration and ARR in our Ghanaian study population." (PMID 36457109, 2022). "Notably, the effects of the GNB3 c.825C>T polymorphism on arterial hypertension among T-allele carriers are restricted to low renin levels." (PMID 36077181, 2022). "-Living at high altitude may predispose to albuminuria and hypertension and renin-angiotensin inhibitors are the preferred drugs in these cases." (PMID 37675017, 2022). "The mechanisms of hypertension in obese children are complex and may be associated with sympathetic activation, renin-angiotensin system activation, inflammation, endothelial dysfunction, and oxidative stress." (PMID 35627657, 2022). "At present, there are several plausible mechanisms to explain the causally link between the SUA and hypertension: SUA can activate renin–angiotensin–aldosterone system, which can lead to retention of water and sodium; SUA can promote generation of reactive oxygen species (ROS)." (PMID 36286298, 2022). "Notably, hypertension has long been recognized to be independently associated with unprovoked seizures, both via direct mechanisms involving the renin-angiotensin system, and indirectly adding an increased predisposition to small vessel disease." (PMID 35295838, 2022). "Our results might be a valuable indicator for hypertension risk prediction and preventive measures, considering renin levels with genetic susceptibility." (PMID 35448080, 2022). "The association between hypertension, elevated creatinine and COVID-19 severity may be related to underlying kidney disease, hypovolemic kidney injury and or some failure of the renin-angiotensin system in response to SARS-CoV-2." (PMID 36260598, 2022). "Given the close link between hypertension and AF, antihypertensive drugs may potentially reduce the risk of AF, especially the renin–angiotensin–aldosterone system inhibitor because of its anti-myocardial remodeling effect." (PMID 36324689, 2022). "The role of vitamin D in the risk of hypertension has been demonstrated in experimental studies, which have indicated that vitamin D may be an endocrine negative regulator of the renin-angiotensin-aldosterone system (RAAS), a key stabilizer of BP balance." (PMID 36364874, 2022). "Earlier studies found that psychosocial stress and anxiety were associated with an increased risk of hypertension, in which the sympathetic nervous system and renin-angiotensin-aldosterone system may play crucial roles." (PMID 35310998, 2022). "Common mechanisms, for instance, upregulation of the renin–angiotensin–aldosterone system, oxidative stress, inflammation, and activation of the immune system, possibly have a role in the association between diabetes and hypertension." (PMID 35455055, 2022). "Finally, other causes of post-transplant hypertension are renin production by failed native kidneys, weight gain after transplantation and chronic renal allograft dysfunction." (PMID 35893294, 2022). "The higher renin activity was associated with ARA especially in the diagnosed hypertension group." (PMID 35003315, 2021). "ACE2 is a key enzyme that regulates the renin-angiotensin system associated with hypertension." (PMID 34067609, 2021). "Furthermore, it was well known that high level of renin-angiotensin (RAS) is an important cause of hypertension." (PMID 33390828, 2021).